INS (insulin)
Diseases named in the same sentence as INS in open-access papers (continued):
Sharing a sentence is not in itself a finding about the gene and the disease.
type 1 diabetes (continued). "Islet cell transplantation is a method to stabilize type 1 diabetes patients with hypoglycemia unawareness and unstable blood glucose levels by reducing insulin dependency and protecting against severe hypoglycemia through restoring endogenous insulin secretion." (PMID 27061400, 2016). "Standard diabetes management for type 1 diabetes is based on exogenous insulin replacements." (PMID 26888412, 2016). "Most misclassifications occurred in patients classed as having type 1 diabetes who had significant endogenous insulin levels (57 out of 601; 9%); most in those diagnosed ≥35 years and treated with insulin from diagnosis, where 37 out of 66 (56%) were misclassified." (PMID 27080317, 2016). "In type 1 diabetes, insulin producing beta cells are targeted for autoimmune destruction." (PMID 27591853, 2016). "In fact, other than facilitating the insulin production process, many believe C-peptide to be useful only as a biomarker for insulin production in patients with type 1 diabetes, due in large part to its longer half-life in the bloodstream (~ 30 min) in comparison to insulin (< 5 min)." (PMID 27528268, 2016). "Insulin requirements in type 1 diabetes can vary between one-third–threefold on a daily basis." (PMID 27364997, 2016). "Notably, some researchers have demonstrated that insulin-producing endocrine cells can be generated from skin fibroblast-derived iPSCs and from fibroblasts isolated from patients with type 1 diabetes." (PMID 27662374, 2016). "The combination of RC and ARX shRNA treatment may facilitate the generation of abundant insulin-producing cells for transplantation into patients with type 1 diabetes." (PMID 26856418, 2016). "This study aimed to investigate associations between HbA1c and eating disorder psychopathology, coping strategies, illness perceptions, and insulin beliefs in young males and females with type 1 diabetes and to assess the extent to which these variables explain the variance in HbA1c." (PMID 26682231, 2016). "Here, we assessed whether glibenclamide could protect the insulin-producing cells against conditions mimicking those expected at the onset of type 1 diabetes." (PMID 28006000, 2016). "If we do not find that RT-CGM is beneficial, then other technologies such as closed-loop insulin delivery, may be indicated to facilitate optimal glycemic control in type 1 diabetes pregnancies." (PMID 27430714, 2016). "Type 1 diabetes mellitus (T1DM) is an autoimmune disease caused by T cell-mediated destruction of pancreatic β cells resulting in the absence of insulin and uncontrolled hyperglycemia." (PMID 26924897, 2016). "Type 1 diabetes is generally thought to be precipitated by an immune-associated, if not directly immune-mediated, destruction of insulin-producing pancreatic β cells." (PMID 27595114, 2016). "Lower insulin doses in obese individuals point to a role of clinical heterogeneity in insulin deficiency rather than normal progression of type 1 diabetes." (PMID 27011769, 2016). "Insulin hypoglycemic action for the same carbohydrate load also is lower in the evening than in the morning as shown by the requirement for a higher evening dose of insulin secretagogue tolbutamide and of insulin in type 1 diabetics." (PMID 27798656, 2016). "In clinical practice, however, despite basal-bolus insulin therapy, quite a few patients with type 1 diabetes are found to exhibit marked glycemic variability, whose whole picture may not be captured by SMBG involving the usual 2–4 measurements a day." (PMID 27478509, 2016). "Hence, our results suggest that OFS can potentially be an effective therapeutic adjunct in the treatment of type 1 diabetes by improving insulin sensitivity and beta-cell function, leading to improved glycemic control." (PMID 27874076, 2016). "One trial in women with type 1 diabetes reported the mean units of insulin used in each group." (PMID 27829574, 2016).
type 1 diabetes (continued). "The low insulin response to glucose seems to be an essential feature of the disease process and suggests that children progressing to type 1 diabetes have an intrinsic impairment in their β-cell mass or function that further deteriorates under environmental pressure." (PMID 26620391, 2016). "Therefore, we aimed to investigate changes in insulin treatment over the last two decades in three age-groups of children and adolescents with type 1 diabetes from Germany and Austria." (PMID 27532627, 2016). "First, recombinant HBV expressing functional protein or RNA could be used to rectify a potentially life-long pathological condition, e.g., insulin for type I diabetes or coagulation factors for hemophilia." (PMID 27171107, 2016). "Low dose, isoform-selective BET inhibitors might also have therapeutic value for Type 1 diabetes patients to boost largely depleted insulin stores." (PMID 27008626, 2016). "Insulin replacement, the only approved therapy for the treatment of type 1 diabetes (T1D), treats the symptoms but not the underlying cause of the disease, namely, immune-mediated destruction of the insulin-producing β cells of the pancreas." (PMID 27727279, 2016). "Type 1 diabetes (T1D) is an autoimmune disease that targets insulin producing β cells." (PMID 26765526, 2016). "We made the rat insulin promoter lymphotoxin (RIPLT) mouse in order to develop a model of type 1 diabetes, since we knew that LT could induce inflammation." (PMID 27881983, 2016). "Patients with type 1 diabetes are an interesting model since glucose and insulin levels can be manipulated, thereby investigating carbohydrate, protein, and fat metabolism (locally and systemically) in the presence of high glucose and low insulin levels or euglycemia and high insulin levels (clamp)." (PMID 27649157, 2016). "Type I diabetes (T1D) is an autoimmune disease caused by an immune response against the β cell antigens in the pancreas, which results in a lack of insulin, but an increase in blood and urine glucose levels." (PMID 27553852, 2016). "Hypoglycemia is the most frequent complication of insulin therapy in patients with type 1 diabetes." (PMID 26521082, 2016). "The treatment of type 1 diabetes is currently based on an intensified insulin therapy, which should mimic the normal insulin secretion, on regular self-monitoring of specific metabolic biomarkers in the patient, and on an education of the patient and his/her family." (PMID 26347009, 2015). "Patients with type 1 diabetes have an absolute requirement for insulin therapy." (PMID 25621692, 2015). "Therefore, it is clinically worthy to investigate the efficacy and safety of switching from twice-daily insulin glargine or detemir to once-daily insulin degludec in type 1 diabetes patients with severely reduced insulin secretion." (PMID 26435713, 2015). "Type 1 diabetes mellitus (T1D) is an autoimmune disease characterized by the infiltration of inflammatory cells into the pancreatic islets of Langerhans, followed by the selective destruction of insulin-producing β-cells, resulting in hyperglycemia." (PMID 26469966, 2015). "Therefore, this study was designed to evaluate data from professional CGM in subjects receiving insulin therapy and determine if this monitoring method can improve the identification of type 1 diabetes." (PMID 25621692, 2015). "IDeg serves as a good option for basal insulin in the treatment of type 1 diabetes." (PMID 26044206, 2015). "The invention of insulin gene therapy substitutes β cell function by generating insulin secretory non-β cells, not vulnerable to autoimmune reactions, offering a prospective therapeutic approach for type 1 diabetes." (PMID 26273667, 2015).
type 1 diabetes (continued). "The medical history of the case showed that he was followed up due to type 1 diabetes for 8 years and for hepatosteatosis for 3 years, had poor blood glucose regulation despite insulin analogue and basal insulin therapy, and was hospitalized and followed up 8–10 times for diabetic ketoacidosis." (PMID 26347835, 2015). "Indeed, increased corneal nerve branch density was the first measure to increase after simultaneous pancreas and kidney transplantation or continuous subcutaneous insulin infusion in type 1 diabetes." (PMID 26578039, 2015). "Type 1 diabetes is mainly due to the reason that the β-cell of pancreas cannot secrete insulin." (PMID 26550021, 2015). "Individuals with type 1 diabetes, in whom insulin secretion is greatly impaired, must therefore supplement their endogenous insulin by a basal-bolus administration of exogenous hormone in order to mimic the physiological regulation of energy metabolism and improve glycaemic control." (PMID 26044206, 2015). "The current result might be related to a lower frequency of nocturnal hypoglycaemia in individuals with type 1 diabetes who use IDeg as basal insulin." (PMID 26044206, 2015). "Type I diabetes (T1D) is known as insulin-dependent diabetes and it is believed to be caused by destruction of beta cells with subsequently absolute lack of insulin." (PMID 25898945, 2015). "Although insulin therapy is an ordinarytreatment for type 1 diabetes, a regimen ofseveral daily injections and need to inject foreach meal may be difficult to achieve optimalglycemic control." (PMID 26199902, 2015). "In type 1 diabetes the insulin-producing beta cells of the pancreas are destroyed." (PMID 26330860, 2015). "Human adipose tissue-derived mesenchymal cells are easily available and autologous in origin, which may provide a source of adipose stem cells-derived insulin producing cells for cell replacement therapy in type 1 diabetes in the future." (PMID 26082830, 2015). "Insulin is one of the most commonly used treatments for type 1 diabetes." (PMID 26002932, 2015). "Among those reporting type I diabetes, fewer than half (29/74) reported taking insulin." (PMID 26307533, 2015). "Also, the impaired insulin secretion in type 1 diabetes increases mitochondrial reactive oxygen species (ROS), causing oxidative stress in all tissues." (PMID 25793188, 2015). "Taking these unique actions of insulin degludec into consideration, switching from twice-daily injections of basal insulin to once-daily injection of insulin degludec could provide great benefit to patients with type 1 diabetes." (PMID 26435713, 2015). "Generation of insulin-producing cells from MSCs is new approach to treat type 1 diabetes." (PMID 26199902, 2015). "In addition, it was reported that the day-to-day variability in plasma glucose in type 1 diabetes patients treated with insulin degludec was lower compared to insulin glargine." (PMID 26435713, 2015). "Furthermore, type 1 diabetes results from autoimmune destruction of insulin synthesizing pancreatic β cells and islet transplantation has been explored as a possible solution for the treatment." (PMID 26273667, 2015). "A replenishable source of insulin-producing cells has the potential to cure type 1 diabetes." (PMID 26457418, 2015). "The disease can affect people of any age, but is most commonly diagnosed in children and young adults, and by the time of diagnosis, patients have very little endogenous insulin production; every year 78,000 children develop type-1 diabetes worldwide (IDF, 2011,)." (PMID 25960780, 2015). "However, even with the introduction of more flexible intensive insulin regimes, people with type 1 diabetes still struggle to achieve optimal glycaemic control." (PMID 26202844, 2015). "(Every patient with type 1 diabetes mellitus should take two types of insulin)." (PMID 25888901, 2015).
type 1 diabetes (continued). "Therefore, protecting number and functions of pancreatic β-cells to maintain insulin secretion would help in regulating blood glucose in type 1 diabetes." (PMID 25793188, 2015). "Type 1 diabetes (T1D) is a highly complex polygenic autoimmune disease resulting in the loss of pancreatic β-cells and absence of insulin production." (PMID 25915398, 2015). "Insulin analogues more closely mimic the pharmacokinetic profile of endogenous insulin, leading to the widespread assumption that they would substantially improve the treatment of patients with type 1 diabetes." (PMID 25964802, 2015). "Other factors that may affect adiponectin include peripheral hyperinsulinemia accompanying subcutaneous insulin administration or the chronic hyperglycemic state of type 1 diabetes." (PMID 25950008, 2015). "Moreover, BBR promoted insulin secretion and protected pancreatic islet cell via antioxidant activity in type 1 diabetes mellitus (T1DM) and late stage of T2DM characterized by damaged islet function." (PMID 25861268, 2015). "Interestingly, reoviruses are known to experimentally induce type 1 diabetes, by inducing insulitis, reduction in insulin content of the pancreas and abnormal glucose tolerance." (PMID 25956355, 2015). "In our experiment, Streptozotocin induces insulitis and subsequent degeneration of the Langerhans islets beta cells, so the model was a mimic of diabetes type 1 as evidenced by the lowered level of insulin, which in fact was very similarly to the patients affected by DM type 1." (PMID 26576637, 2015). "Introduction of lentiviral PDX-1 significantly induces hAMSCs to differentiate into islet-like cell aggregates, which may provide a source of adipose stem cells-derived insulin-producing cells for cell replacement therapy in type 1 diabetes." (PMID 26082830, 2015). "The objective of this study was to evaluate the feasibility and acceptability of decision coaching guided by the Ottawa Family Decision Guide with children and parents considering insulin delivery options for type 1 diabetes (insulin pump, multiple daily injections, or standard insulin injections)." (PMID 25889602, 2015). "The strength of our study is the evaluation of insulin kinetics in an underserved population of young children with type 1 diabetes who may benefit from insulin dilution through reduced variability in insulin absorption." (PMID 25537835, 2015). "From the final 10 pharmacies, a total of 336 questionnaires were distributed and 204 were returned; however, eight patients reported the use of insulin at the beginning of their therapies and were deemed to have type 1 diabetes, leaving a sample size of 196 (a response rate of 58.3%)." (PMID 26713231, 2015). "Yet, the management of Type 1 diabetes is still psychologically complex, as improved technology does not change the challenge of psychologically dealing with choices such as insulin dosage and cognitive and emotional reactions to high and low blood sugar levels." (PMID 25303963, 2014). "However, increasing physical activity often creates a challenge for people with type 1 diabetes, because of difficulties maintaining euglycemia in the face of altered food intake and adjustments to insulin doses." (PMID 24826899, 2014). "Being able to manage and adjust insulin doses is a key part of managing type-1 diabetes." (PMID 25563223, 2014). "This young lady with type 1 diabetes initially presented with circulating anti-insulin antibodies." (PMID 24711924, 2014). "This study has several strengths including the large population-based sample, prospective design allowing 10 years of follow-up, inclusion of both men and women, detailed fracture data, and the ability to differentiate between insulin-dependent and non-insulin-dependent diabetes." (PMID 24919660, 2014). "In European children, insulin use essentially indicates a diagnosis of Type 1 diabetes." (PMID 24886413, 2014).
type 1 diabetes (continued). "C-peptide is co-secreted with insulin by the pancreas, as a by-product of the enzymatic cleavage of proinsulin to insulin, and, in patients diagnosed with type 1 diabetes, C-peptide levels decline rapidly because of the autoimmune destruction or inactivation of beta cells." (PMID 24264051, 2014). "Type 1 diabetes patients depend on external insulin (usually injected subcutaneously) for survival." (PMID 25574400, 2014). "Taken together, the experimental data suggests that linkage of the weak adjuvant CTB to the dominant type 1 diabetes autoantigens INS and GAD inhibits DC maturation through downregulation of major DC costimulatory factors and inflammatory cytokine biosynthesis." (PMID 24877157, 2014). "Only 7 patients classified as having type 1 diabetes by the computer-based diagnostic algorithm did not receive insulin during the follow-up." (PMID 24963628, 2014). "Type 1 diabetes (T1D) is characterized by immune-mediated destruction of the insulin-secreting β cells in the pancreatic islets as a result of an unknown trigger mechanism." (PMID 24741589, 2014). "Furthermore, the researchers showed that, in a mouse model of type 1 diabetes, leptin was as effective as insulin in controlling blood sugar; nevertheless the mechanism of action is far from clear." (PMID 24639883, 2014). "Moreover, there has been no controlled clinical trial to determine the amount of human fetal pancreas and the number of transplantations needed to achieve insulin production in type I diabetes." (PMID 25526563, 2014). "None of the subjects was able to discontinue insulin therapy, consistent with their absolute insulin deficiency and type 1 diabetes, but all auxiliary oral and injectable therapy was discontinued after surgery." (PMID 24668543, 2014). "Similarly, FN1 transcript levels were reduced during type 1 diabetes and further lowered in scWAT and rWAT and only slightly increased in eWAT by insulin." (PMID 25170835, 2014). "In Type 1 Diabetes (T1D), the use of recombinant insulin to maintain normoglycemia does not address the underlying cause of the disease, T cell mediated β cell destruction." (PMID 26779386, 2014). "Recently, the researchers have shown that leptin could substitute for insulin to control blood sugar fluctuations in patients with type 1 diabetes." (PMID 24639883, 2014). "This may ultimately contribute to exhaustion of insulin in the islets and frank manifestation of insulin-dependent diabetes in DBA/2J mice." (PMID 25705631, 2014). "Physical activity interventions in people with type 1 diabetes have been linked to improved CRF, insulin sensitivity, lipid profile and endothelium function, but results investigating the association between levels of physical activity and glycaemic control have been contradictory." (PMID 24826899, 2014). "For example, regular insulin injections may be sufficient to secure a normal quality-of-life for many patients with type I diabetes." (PMID 24575864, 2014). "We surmise, based on our experimental results, that insulin directly may exert an important hypotensive action when given to type 1 diabetes patients." (PMID 24400109, 2014). "Additionally, a further challenge facing people with type 1 diabetes is how best to ensure good glucose control in the presence of varying levels of food intake and insulin doses throughout the day." (PMID 24826899, 2014). "Type 1 diabetes can be treated in a palliative fashion with exogenous insulin injection." (PMID 24877157, 2014). "However, there have been a few cases worldwide where patients with type 1 diabetes treated with recombinant human insulin have developed a high titre of circulating insulin antibodies." (PMID 24711924, 2014). "Intensive insulin therapy is invaluable in treatment of type 1 diabetes." (PMID 24860609, 2014).